INS (insulin)
Diseases named in the same sentence as INS in open-access papers (continued):
Sharing a sentence is not in itself a finding about the gene and the disease.
type 2 diabetes (continued). "There is increasing evidence suggesting that dietary omega-3 polyunsaturated fatty acids (n-3 PUFA), particularly the long-chain fatty acids eicosapentaenoic acid (EPA) and docosahexaenoic acid (DHA) found in marine oils, may improve insulin sensitivity or reduce the incidence of type 2 diabetes." (PMID 25331725, 2014). "A clinical randomized double-blind vehicle-controlled trial recruiting 63 type 2 diabetic patients with hypomagnesemia receiving glibenclamide has shown that supplementation of magnesium (2.5 g MgCl2/day) for 4 months improved HbA1c, fasting glucose as well as insulin levels." (PMID 25160946, 2014). "Vitamin D seems to contribute to obesity and type 2 diabetes control by several mechanisms, including the regulation of adipogenesis during adipocyte differentiation, the stimulation of insulin synthesis and protection of pancreatic β-cells, and reducing insulin resistance in muscles." (PMID 24747593, 2014). "However, this study demonstrated that an oral incretin-based treatment strategy employing sitagliptin and insulin glargine may be safe and effective in patients with type 2 diabetes who have developed RHGT." (PMID 24738001, 2014). "Though only 38 diabetic subjects were recruited in our study group, the E23K polymorphism still contributed to a significantly increased risk for type 2 diabetes independent of age, gender, BMI age- and sex-specific percentiles, and fasting plasma insulin level." (PMID 25309595, 2014). "The majority of people with type 2 diabetes (T2D) receive their care in general practice and will eventually require initiation of insulin as part of their management." (PMID 25361788, 2014). "For example, studies have shown that the female hormone, 17β-estradiol, can increase insulin production in the pancreas, but that the chemical bisphenol A can overstimulate the estrogen receptor potentially leading to insulin resistance – an important component of type 2 diabetes." (PMID 25533907, 2014). "The primary aim of this randomized controlled trial is to examine whether a community-based PRT programme combined with additional whey-protein and vitamin D can promote greater improvements in glycaemic control and insulin sensitivity than PRT alone in older adults with type 2 diabetes." (PMID 25376884, 2014). "Insulin initiation and titration in primary care is necessary to respond to the growing epidemic of type 2 diabetes (T2D)." (PMID 24886287, 2014). "For example, BDNF, a growth factor responsible for neuronal growth and survival, is decreased in patients with type 2 diabetes mellitus (T2DM), indicative of insulin sensitivity." (PMID 24473138, 2014). "In our study, we found that LDR-induced renal protection against type 2 diabetes was independent of hypoglycemic effects but associated with improving insulin sensitivity, which might be attributed to activation of the Akt signaling pathway." (PMID 24651118, 2014). "In similar generalised linear regression models the PPARG allele C (Pro12) increased 2 hour insulin levels in the overall cohort (p = 0.009) and in the non-diabetic group only (p = 0.0003) after stratification by type 2 diabetes status, with a significant statistical interaction (p = 0.017)." (PMID 24447396, 2014). "Therefore, ROS-promoted autophagy maturation may contribute to the maintenance of intracellular insulin content in β-cells in the settings of insulin secretory dysfunction, such as type 2 diabetes." (PMID 24912985, 2014). "Previous studies have shown that ER stress may impair insulin action in adipocytes and hepatocytes, as well as reduce insulin secretion from pancreatic islet beta cells; in such settings, a relative deficit in the UPR may play a causal role in the development of type 2 diabetes." (PMID 24465394, 2014). "Type 2 diabetes mellitus (T2DM) is a complex metabolic disorder characterized by hyperglycemia as a result of pancreatic beta cell dysfunction and insulin resistance." (PMID 25062844, 2014).
type 2 diabetes (continued). "Glucose transport in insulin-sensitive tissues (skeletal muscle and adipose tissue) is a control point for the regulation of blood glucose levels, and a possible target for the derangement of glucose homeostasis in certain disease states, such as type 2 diabetes." (PMID 24748202, 2014). "Therefore, SU and DPP4 inhibitor may be an effective combination for supporting inappropriate insulin secretion in type 2 diabetes." (PMID 24578754, 2014). "However, fasting insulin may have been affected by exogenous insulin use in persons with type 1 diabetes and fasting insulin values had a strongly skewed distribution in persons with type 2 diabetes." (PMID 24438170, 2014). "Type 2 diabetes can often initially be controlled with diet and exercise (lifestyle changes) and with antidiabetic drugs such as metformin and sulfonylureas, but patients may eventually need insulin injections to control their blood sugar levels." (PMID 24845081, 2014). "We hypothesized that in type 2 diabetes, the dysfunctional pancreas compensates for amylin in a similar pattern it does for insulin by increasing its secretion at an early stage and declining greatly then diminishing leading to cognitive decline at a late stage of the disease." (PMID 25750761, 2014). "However, as the type 2 diabetes develops, the insulin secretion is becoming insufficient." (PMID 25202328, 2014). "According to an earlier epidemiological investigation, an impaired insulin sensitivity was observed in small for gestational age (SGA) children, which may contribute to enhanced risk of type II diabetes in adulthood, especially in SGA children with catch-up growth and a high body mass index (BMI)." (PMID 25479255, 2014). "A majority of genes associated with type 2 diabetes from this meta-analysis (ADCY5, CDKAL1, CDKN2A/B, HHEX, IGF2BP2, SLC30A8, TCF7L2 and KCNQ1) are involved in pancreatic beta cell function, while two are implicated in insulin sensitivity (PPARG) and adiposity (FTO)." (PMID 25145545, 2014). "We have previously shown that genetic predisposition for type 2 diabetes, but not obesity, is associated with inappropriate expansion of the adipose cells for small increases in body fat and that this is associated with reduced insulin sensitivity." (PMID 25148116, 2014). "Recognized ß-cell abnormalities in type 2 diabetes include dysrhythmic pulsatile insulin secretion, defective glucose potentiation of responses to non-glucose insulin secretagogues, increased plasma pro-insulin to insulin ratio, and accumulation of islet amyloid polypeptide." (PMID 25945127, 2014). "Daily vitamin D and calcium supplementation for 6 months may not change OGTT-derived measures of insulin sensitivity, insulin secretion and β-cell function in multi-ethnic adults with low vitamin D status at risk of type 2 diabetes." (PMID 25299668, 2014). "However, as far as we know, this study may be the first study in Chinese type 2 diabetes patients to assess the relationship of 25-(OH)D and insulin secretion and sensitivity as well as the relationship of 25-(OH)D and urine ACR." (PMID 24868538, 2014). "While some of them found that insulin sensitivity decreases with age, others shown that plasma glucose clearance was found to be dependent on the waist-to-hip ratio and not age, with the exception of older people with pre-existing impaired glucose tolerance or type 2 diabetes." (PMID 24672805, 2014). "For instance, in overweight, obese, and type 2 diabetes cohorts, 60-second bouts of exercise at near-maximal capacity, with 60–120-second recovery periods, led to significant improvements in glucose control, insulin sensitivity, and skeletal muscle oxidative capacity." (PMID 24669314, 2014). "Our findings were in line with a previous observation suggesting that the use of rapid-acting insulin analogue glulisine could be associated with a risk reduction of 24% for macrovascular events in patients with type 2 diabetes as compared with the use of human regular insulin." (PMID 24244557, 2013).
type 2 diabetes (continued). "However, few studies have examined sleep quality in patients with type 2 diabetes using insulin." (PMID 23383010, 2013). "In conclusion, the results from this trial demonstrated that the basal insulin, IDeg, as add-on to 1–2 OADs dosed once daily at any time of the day, was superior to Sita in terms of improving glycaemic control as measured by reduction in HbA1c in subjects with type 2 diabetes." (PMID 23577643, 2013). "Mechanisms whereby altered TCF7L2 production and/or function may contribute to the development of type 2 diabetes are not fully understood but likely include a decrease in β-cell mass, impaired insulin processing or release, and impaired incretin signaling in β-cells." (PMID 24324494, 2013). "Notably, participants were free of diagnosed type 2 diabetes and our findings held when controlling for other factors that may relate to decreased insulin sensitivity, namely age and waist circumference." (PMID 24358272, 2013). "The meal-driven, graduated progression of insulin therapy in this way, rather than immediately embarking on a full basal–bolus regimen or introducing premixed insulin preparations, may be more relevant and acceptable to a large number of persons with Type 2 diabetes and their physicians alike." (PMID 22998363, 2013). "The purpose of this study is to compare central obesity, insulin sensitivity, and cardiovascular disease risk factors between premenopausal and postmenopausal women with a history of gestational diabetes mellitus (GDM), controls, and women with type 2 diabetes (T2DM)." (PMID 23781323, 2013). "Given the close relation between depression and negative appraisals of insulin therapy in insulin-naïve people with type 2 diabetes, it is of special clinical interest to examine whether the negative motivational aspects of depression may lead to a delay in insulin initiation." (PMID 24223860, 2013). "Although the downstream mechanisms underlying these observations are not clear, they are consistent with the idea that PPAR-α plays a critical role in regulating insulin sensitivity in vivo and that its activation may lead to the delay of onset of type 2 diabetes." (PMID 23781121, 2013). "HBOT (2.5ATA, 1 hr X 10 sessions) improved the metabolic control and reduced insulin requirements in patients with type 2 diabetes mellitus (T2DM) after stem cell transplantation." (PMID 23510433, 2013). "The effects of tesaglitazar on augmenting insulin mediated control of hepatic and skeletal muscle glucose metabolism are consistent with the results of a number of studies with other PPARγ agonists on glucose metabolism in both animal models and even patients with type 2 diabetes." (PMID 24285952, 2013). "Adding liraglutide to insulin also induced a significant reduction in body weight and waist circumference, suggesting that Liraglutide may be the best treatment option for poorly controlled type 2 Diabetes and abdominal obesity." (PMID 23777457, 2013). "Another gene that has been associated with type II diabetes and shows higher gene transcript levels in DD, is angiopoietin-like 4 (ANGPTL4), a glycosylated, secreted protein with a fibrinogen C-terminal domain involved in glucose homeostasis, lipid metabolism and insulin sensitivity." (PMID 23554969, 2013). "Our findings suggest that this novel mechanism of CaMKII-mediated phosphorylation of RyR2 in pancreatic β cells contributes to the development of type 2 diabetes and may aid in the development of future therapeutic targets to regulate insulin secretion under pathological conditions." (PMID 23516528, 2013). "Also, this type 2 diabetes will require insulin therapy early on." (PMID 23374611, 2013). "This treatment acts independently of β-cell function or insulin sensitivity, thereby suggesting an alternative or complementary approach to currently available treatments and offering an additional therapeutic option throughout the natural history of type 2 diabetes." (PMID 23425012, 2013).
type 2 diabetes (continued). "The incretin effect has been shown to be reduced in patients with type 2 diabetes (T2D), in prediabetic states such as impaired glucose tolerance and in obese, insulin resistant subjects with NGT." (PMID 24019903, 2013). "However, despite these limitations, this study provides useful information for clinical practice and may serve to aid the ongoing development of insulin treatment regimens specifically for patients with type 2 diabetes." (PMID 24223662, 2013). "The increased iNOS staining observed in the islets of PBS-treated db/db mice may also contribute to β-cell dysfunction as iNOS-derived nitric oxide inhibits insulin secretion from β-cells in vitro and, furthermore, iNOS inhibitors ameliorate β-cell dysfunction in rodent models of type 2 diabetes." (PMID 24205160, 2013). "Family physicians received insulin initiation/titration education, a physician-specific ‘report card’ on the characteristics of their type 2 diabetes (T2DM) population, and a registry of insulin-eligible patients at a workshop." (PMID 23433347, 2013). "This is in line with a requirement for large insulin amounts to handle the large carbohydrate intake of the low-fat diet and suggests the low-carbohydrate diet to be preferable regarding glycemic control in patients with type 2 diabetes when compared with a low-fat diet." (PMID 24312178, 2013). "Common and low-frequency variants in AGPAT6 do not significantly associate with type 2 diabetes susceptibility, or influence related phenotypic traits such as obesity, dyslipidemia or indices of insulin sensitivity or insulin secretion in the population studied." (PMID 24156295, 2013). "Thus, we conclude that EA stimulation at a specific acupoint may have an important potential role for the treatment of type 2 diabetes because this treatment is able to enhance insulin activity." (PMID 23983807, 2013). "The pathophysiology of NODAT closely mimics that of type 2 diabetes mellitus (T2DM), with both diseases characterized by a combination of insulin resistance and insulin hyposecretion." (PMID 22569928, 2012). "Thus, CR may be an effective way to increase mitochondrial biogenesis in a wide range of species and tissues; however, more studies are required to characterize its role in insulin signaling in muscle from type 2 diabetics." (PMID 22203837, 2012). "Thus, insulin and/or leptin resistance in skeletal muscle may play a significant role in the pathogenesis of obesity and type 2 diabetes." (PMID 23115649, 2012). "Treatment of diabetic db/db mice with an iNOS inhibitor reversed hyperglycaemia and improved insulin sensitivity, showing that the down-regulation of iNOS mRNA in macrophages is the molecular target for the prevention of not only inflammation but also type-2 diabetes." (PMID 22611357, 2012). "Thiazolidinediones (TZDs) act through PPARγ to elicit increased sensitivity to insulin in type 2 diabetes mellitus (T2DM) and reduce inflammation in arteries." (PMID 22649490, 2012). "While the concordance estimates from population-based twin studies questioned the notion of a major genetic component in type 2 diabetes, perhaps the most significant lesson from twin studies was the finding that zygosity—and thus twin status—may influence insulin secretion and insulin action." (PMID 22643933, 2012). "Therefore we examined the possibility that direct AT2 receptor stimulation by compound 21 (C21) might contribute to possible insulin-sensitizing/anti-diabetic effects in type 2 diabetes (T2DM) with PPARγ activation, mainly focusing on adipose tissue." (PMID 23155382, 2012). "Since short-term continuous subcutaneous insulin infusion decreases the plasma vaspin levels associated with improvements in insulin sensitivity, the serum vaspin levels may be influenced by both therapeutic modalities and the status of intrinsic insulin secretion in patients with type 2 diabetes." (PMID 23206815, 2012).
type 2 diabetes (continued). "Higher prevalence indicated by GP diagnosis than by prescription data could be explained by prescription of insulin by hospital doctors for young adults, and attainment of adequate diabetic control by change in life style for many patients with diabetes type II." (PMID 22978749, 2012). "Thus, the addition of twice-daily exenatide to titrated insulin glargine may be considered in multiple types of patients with type 2 diabetes that have sub-optimal glycaemic control." (PMID 23061886, 2012). "In patients with type 2 diabetes, clinical studies indicate that adding exenatide twice daily to basal insulin results in robust reductions in HbA1c, modest weight reduction, no significant increase in hypoglycaemia and (in observational studies) a possible reduction in insulin dose." (PMID 23061886, 2012). "The potentiality of the Ma-Pi macrobiotic diet as therapeutic instrument for the rapid metabolic control of type 2 diabetic patients is supported by the positive effects observed at short term (21 days) on the glucose and lipid metabolism, blood pressure, body composition, and insulin consumption." (PMID 23097695, 2012). "Therefore, results from these admitted patients could help us for better learning insulin regimen in Chinese type 2 diabetic patients." (PMID 22720003, 2012). "In view of the important role of ADMA in regulating endothelium-dependent vasodilation and, thereby, insulin sensitivity, we hypothesized that polymorphisms in the DDAH2 gene, potentially altering its expression or activity, may be associated with type 2 diabetes." (PMID 22558392, 2012). "Glucagon-like peptide-1 receptor (GLP-1R) agonists have been investigated for treating type 2 diabetes mellitus (T2DM) since the early 1990s because of their ability to enhance glucose-dependent insulin secretion." (PMID 21167014, 2012). "Furthermore, pro-inflammatory cytokines were reported to have deleterious effects on pancreatic β-cells which could lead to an insufficient response to insulin resistance, resulting in onset of type 2 diabetes." (PMID 22929089, 2012). "Therefore, it might be involved in the impairment of insulin secretion considered as a dominant factor in type 2 diabetes pathogenesis." (PMID 22927833, 2012). "Interestingly, addition of essential amino acids to a diet in poorly regulated elderly patients with type 2 diabetes improved metabolic control and lowered fasting blood glucose and serum insulin levels, as well as lowered levels of glycated hemoglobin (HbA1c)." (PMID 22647249, 2012). "Thus, it would be important that all future trials describe 25OHD serum levels at the baseline and investigate not only blood glucose but also the role of vitamin D on glucose tolerance, insulin secretion, insulin sensitivity and ultimately with incident of type 2 diabetes." (PMID 22347618, 2012). "We hypothesis that the effectiveness of genipin on ameliorating the symptoms of both type 1 and type 2 diabetes might probably independent of insulin and blood glucose level, whose underlying mechanism needs further investigation." (PMID 22848482, 2012). "Overall, data from randomized trial do not support the hypothesis that insulin therapy increases the risk of cancer in patients with type 2 diabetes." (PMID 23209929, 2012). "Disruption of normal glucose homeostasis and substantial elevations of fasting glucose are hallmarks of type 2 diabetes (T2D) and typically result from sustained reduction in pancreatic beta-cell function and insulin secretion." (PMID 23226241, 2012). "This observational study investigated whether blood glucose control is related to the quality of health care provided to patients with non-insulin-treated Type 2 diabetes and also assessed other factors that might influence the achievement of current HbA1c goals." (PMID 21294772, 2011).